ZNF251 (zinc finger protein 251)
Description:
May be involved in transcriptional regulation.
Tractability: PROTAC: UniProt records ubiquitination sites on it; ubiquitination databases record sites on it.
Gene: Protein-coding gene on chromosome 8 (144,720,515 to 144,756,417, reverse strand). Ensembl gene ENSG00000198169.
Subcellular location: Nucleus
Subcellular location (Human Protein Atlas): Nucleoplasm; Cytosol
Gene Ontology:
Molecular function: protein binding; DNA-binding transcription factor activity, RNA polymerase II-specific; RNA polymerase II cis-regulatory region sequence-specific DNA binding; sequence-specific DNA binding
Biological process: regulation of transcription by RNA polymerase II; regulation of DNA-templated transcription
Cellular component: nucleus
Genetic constraint (gnomAD): Loss-of-function variants: 5 observed, 5.07 expected, observed/expected ratio (o/e) 0.99, 90% interval 0.51 to 1.8. That is too few expected variants to judge how well the gene tolerates losing a copy. Missense variants: 691 observed, 755.59 expected, observed/expected ratio (o/e) 0.91, 90% interval 0.86 to 0.97. Synonymous variants: 253 observed, 257.65 expected, observed/expected ratio (o/e) 0.98, 90% interval 0.88 to 1.09.
Homologues: Orthologues: chimpanzee ZNF251 (99% identical), macaque ZNF251 (95% identical), rat Zfp251 (70% identical), mouse Zfp251 (69% identical), pig ZNF251 (67% identical). Paralogues in human: ZNF543 (34% identical), ZNF724 (32% identical), ZNF841 (32% identical), ZNF585B (32% identical), ZNF28 (32% identical), ZNF267 (32% identical), ZNF41 (32% identical), ZNF546 (32% identical), ZNF568 (32% identical), ZNF658 (32% identical), ZNF726 (32% identical), ZNF254 (32% identical), and 164 more.
Diseases named in the same sentence as ZNF251 in open-access papers:
ZNF251 is named in the same sentence as 6 diseases in open-access papers, as found by Europe PMC text mining. Sharing a sentence is not in itself a finding about the gene and the disease. The quoted sentences say what the papers report.
acute myeloid leukemia (1 paper, 2023). Acute myeloid leukemia (AML) is a group of neoplasms arising from precursor cells committed to the myeloid cell-line differentiation. "Moreover, cohorts of acute myeloid leukemias (AMLs) display low levels of ZNF251 which may affect the outcome of clinical trials with PARPis18." (PMID 37066268, 2023).
breast carcinoma (1 paper, 2023). "This indicates that ZNF251 haploinsufficiency confers resistance to platinum-based drugs in BRCA1-mutated breast cancer cells." (PMID 37066268, 2023). "To further validate whether deficiency of ZNF251 confers resistance to olaparib, we used three newly designed sgRNAs to disrupt ZNF251 in the MDA-MB-436 breast cancer cell line." (PMID 37066268, 2023). "We found that ZNF251 knockdown caused olaparib resistance in BRCA1-mutated but not BRCA1-wildtype breast cancer cells." (PMID 37066268, 2023). "Furthermore, using CellMiner database analysis, we found that ZNF251 expression is also positively correlated with sensitivity to olaparib, cisplatin, and carboplatin in breast cancer cells." (PMID 37066268, 2023).
ovarian carcinoma (1 paper, 2023). A malignant neoplasm originating from the surface ovarian epithelium. "Our study revealed that ZNF251, a transcription factor, is a novel gene whose haploinsufficiency confers PARPi resistance in multiple breast and ovarian cancer lines harboring BRCA1 mutations." (PMID 37066268, 2023). "Using a positive whole-genome CRISPR/Cas9 library screen, and several BRCA1-mutated breast and ovarian cancer cell lines we discovered that haploinsufficiency of ZNF251 which belongs to the Kruppel-associated box (KRAB) zinc-finger gene family cluster caused resistance to multiple PARPis." (PMID 37066268, 2023).
cancer (2 papers, 2023 to 2025). A tumor composed of atypical neoplastic, often pleomorphic cells that invade other tissues. "Our findings reveal that haploinsufficiency in zinc finger 251, resulting in partial knockdown of ZNF251 protein (referred to as ZNF251KD), causes resistance to olaparib in multiple BRCA1-mutated cancer cell lines." (PMID 37066268, 2023). "Taken together, downregulation of ZNF251 was associated with resistance to olaparib and/or platinum derivatives in breast and/or ovarian BRCA1-mutated cancer cells." (PMID 37066268, 2023). "Mechanistically, we discovered that ZNF251 haploinsufficiency leads to constitutive stimulation of DNA-PKcs-dependent non-homologous end joining (NHEJ) repair of DSBs and DNA-PKcs-mediated fork protection in BRCA1-mutated cancer cells (BRCA1mut + ZNF251KD)." (PMID 37066268, 2023).
ZNF251 also shares sentences with these, for which no sentence is quoted: pancreatic cancer (1 paper); tumor (1).